APC (APC regulator of Wnt signaling pathway)
Diseases named in the same sentence as APC in open-access papers (continued):
Sharing a sentence is not in itself a finding about the gene and the disease.
colorectal tumors (continued). "Of these, we selected 30 transcription factors and used siRNA-mediated knockdown to ask whether suppression of any of them affects Asef expression in the colorectal tumor cell lines DLD-1, which contain truncated APC." (PMID 24244701, 2013). "Importantly, our analyses revealed that, while known CRC driver genes APC and SMAD4 were disrupted in both human colorectal tumors and tumors from ApcMin/+ mice, the questionable MCC gene was disrupted in human tumors but appeared to be intact in mouse tumors." (PMID 20707908, 2010). "Somatic G → T mutations in the APC and KRAS genes are frequently observed in such colorectal tumors in MAP patients, and even in non-MAP patients, reduced MUTYH expression is associated with an increased number of somatic G → T mutations in prostate adenocarcinoma." (PMID 29098062, 2017). "Since the APC/Wnt/β-catenin pathway is known to play a major role in colorectal carcinogenesis and since both CK1 isoforms play regulatory roles in Wnt signaling it can be speculated that overexpression of CK1α and δ leads to a Wnt/β-catenin-dependent malignant phenotype of colorectal tumor cells." (PMID 29409464, 2018).
gastric cancer (128 papers, 1996 to 2026). A primary or metastatic malignant neoplasm involving the stomach. "Adenomatous polyposis coli (APC) is widely known as a tumor suppressor, with mutations in this gene found in ~80% of human colorectal cancers, as well as in many pancreatic and gastric cancers." (PMID 40985218, 2025). "One of the studies showed that 46 out of 52 samples of stomach adenocarcinoma, a common type of gastric cancer, displayed nonsynonymous mutations in APC genes." (PMID 39936971, 2025). "The combination of KRAS activation and APC loss recapitulates the cooperative effects observed in human gastric cancers with both alterations, which typically show more aggressive behavior." (PMID 40673273, 2025). "Mutations in APC were also frequent in gastric cancers with CDX2 induction and SOX2 suppression (16.2% of cases), and the difference in prevalence compared with SOX2-maintained-expression cancers approached significance (Fisher’s exact test with p = 0.06)." (PMID 40149431, 2025). "The APC mutation is found in ~80% of human colorectal cancers, as well as pancreatic and gastric cancers." (PMID 40985218, 2025). "APC gene mutations play a crucial role in the carcinogenesis of intestinal type gastric cancer, independently of MSI status." (PMID 39669365, 2024). "Given the potential biological relevance of APC in gastric cancer development, we analyzed its mutational frequency at different stages." (PMID 39314047, 2024). "Patients with a pathogenic variant in the APC promoter 1B region have an increased risk of gastric polyposis and early-onset gastric cancer." (PMID 39039610, 2024). "Case studies have identified novel frameshift mutations in APC, which leave individuals susceptible to gastric cancer after Helicobacter pylori infection." (PMID 38562145, 2024). "Although APC mutations have been detected in 7%–34% of gastric cancer, patients with FAP are at only a 0.5%–1.3% lifetime risk of developing gastric cancer." (PMID 37943618, 2023). "Case 3 was a woman in her 40 s who was diagnosed with gastric cancer with multiple polyps in the stomach and a mutation of APC exon 1B." (PMID 35435526, 2022). "When comparing molecular alteration differences between SBA and gastric carcinoma, variation in the APC mutation rate was also striking, with one study demonstrating 27% incidence of APC mutations in SBA as compared to just 8% in gastric adenocarcinoma." (PMID 35267592, 2022). "APC counteracts proliferation, facilitates apoptosis, and suppresses tumor progression, thus APC-deficient tumors drive colorectal and gastric cancers." (PMID 34032581, 2021). "For example, 37% of APC-mutant gastric cancers have mutation in RNF43, suggesting a compound activation of Wnt signaling in the same tumor." (PMID 34552611, 2021). "For instance, APC mutations were found already in low-grade dysplasia and were less frequent during the progression of gastric cancer." (PMID 31248166, 2019). "Apart from that, loss-of-function mutations of genes that inhibit or limit Wnt signaling were observed: Mutations in the APC gene have been reported in 7%, 15–18% or even 30–34% of gastric cancer samples." (PMID 31248166, 2019). "Mutations in exon 15 of APC gene were detected in 40% of gastric cancers and are similar to the previous studies." (PMID 28576136, 2017). "The mutations of APC have also been identified in gastric adenoma and intestinal metaplasia, indicating that they occur during preneoplastic stage of gastric cancer development." (PMID 25945346, 2015). "Studies have reported the detection of APC mutations in 12 of 46 gastric cancers, with β-catenin nuclear localization occurring in both diffuse- and intestinal-type gastric cancers at a higher rate." (PMID 26529010, 2015). "For example, both humans (FAP) and mice with APC mutations, which affect Wnt signalling, develop cancers predominantly in the antrum establishing the L-GPCs as a potential cell of origin for gastric cancer." (PMID 26287172, 2015).
gastric cancer (continued). "Mutations of the Wnt pathway genes APC and β-catenin can only be detected in a small portion of gastric carcinomas." (PMID 26689843, 2015). "APC mutations are rare in extracolonic cancers, including gastric carcinomas, with less than 10% of both differentiated and undifferentiated gastric carcinomas containing such mutations." (PMID 22723903, 2012). "We examined 26 gastric carcinomas from British patients for mutations of the APC gene using a single-strand conformation polymorphism (SSCP) and heteroduplex assay in conjunction with the protein truncation test (PTT)." (PMID 8855982, 1996). "The increased rate of mutations in the WNT/APC/β-catenin pathway observed in CDX2-induced gastric cancers with SOX2 suppression may serve to reinforce CDX2 expression in these cancers, as WNT signaling is an inducer of CDX2 transcription." (PMID 40149431, 2025). "Concurrent KRAS and APC variants are uncommon in gastric cancer." (PMID 40916582, 2025). "However, DNA damage caused by H. pylori infection was also more severe when the APC gene was inactivated, a finding that suggests a role for APC in the association between H. pylori infection and gastric cancer development." (PMID 39468464, 2024). "Gastric cancer in the pediatric age group is rare and usually associated with recognized polyposis germline mutations (APC for familial adenomatosis polyposis coli and STK11 for Peutz–Jeghers syndrome) and E-cadherin mutations in patients as young as 15 years old or younger." (PMID 37754493, 2023). "LINC01133 inhibits the occurrence and metastasis of gastric cancer through the regulation of adenomatous polyposis coli (APC) gene expression and the Wnt-β-catenin pathway by competitive adsorption of miR-106a-3p, and is associated with good prognosis in gastric cancer patients." (PMID 35399076, 2022). "In addition, some gastric cancer cell lines used in this study suffer mutations in APC (HGC27, MKN45, and MKN28) or CTNNB1 (AGS)." (PMID 35805009, 2022). "Notably, the detection of the germline APC variant in the present epidemiological study led to the early detection of gastric cancer in a JRT." (PMID 35717217, 2022). "Moreover, a high APC (203525_s_at) expression level was associated with poor OS (P = 0.00019) for gastric cancer and poor OS (P = 0.00053) and PPS (P = 0.00038) for lung cancer." (PMID 35303016, 2022). "Around 18% of gastric cancers have mutations in APC and RNF43 as the primary cause of the disease." (PMID 34552611, 2021). "Our results indicate that APC down-regulation is also an important risk factor to the development of gastric cancer and that this gene may have a crucial function in gastrointestinal malignant neoplasia." (PMID 30376837, 2018). "Indeed, different components of the Wnt pathway have been shown to be mutated or dysregulated in gastric cancer, including Wnt1, SFRPs, Axin1 and Axin2, APC, GSK3-β, and β-catenin." (PMID 28230774, 2017). "Due to exon 14 mutation, APC protein might be truncated and the same phenomenon might occurin gastric cancer leading to aneuploidy and G1 phase arrest followed by high S phase in cell cycle for diffuse type gastric cancer." (PMID 28576136, 2017). "Note that the APC/Wnt pathway is already validated as a pathway associated to gastric cancer." (PMID 27832067, 2016). "Mutations in APC are frequently observed in gastric adenomas, but only rarely in gastric cancers." (PMID 25997695, 2015). "In conclusion, losses of a CNV at 5q22 (Variation 7468), especially in the DNA region surrounding APC-exon 9, may be associated with a higher risk of gastric cancer." (PMID 25210923, 2014).
gastric cancer (continued). "Losses of a CNV at 5q22, especially in the DNA region surrounding APC-exon 9, may be associated with a higher risk of gastric cancer." (PMID 25210923, 2014). "Moreover, gene FBXO11, XPO1, SLC3A2, and APC, whose mutation detections may be affected by various tumor purities in gastric cancer, were closely related with cancer occurrence and development." (PMID 33425983, 2020). "This leads to a high TMB development in these cancers, which also acquire increased levels of mutations in several other genes associated with gastric cancer, such as in receptor tyrosine kinase pathways and the WNT/APC/β-catenin pathway." (PMID 40149431, 2025). "In gastric cancer tissue, elevated levels of Wnt proteins, FZD7 receptor, and LRP5/6, along with β-catenin accumulation and reduced APC expression, are associated with poor prognosis." (PMID 40943055, 2025). "Dysregulated Wnt signaling affects almost 50% of gastric cancers, with the most commonly mutated genes being RNF43, AXIN1/2, CTNNB1, and APC." (PMID 39191487, 2024). "For instance, the altered expression of LINC01133 in gastric cancer regulates the Wnt/β-Catenin signaling pathway through the miR-106a-3p/APC axis." (PMID 39519092, 2024). "For instance, LINC01133 inhibits epithelial–mesenchymal transition in gastric cancer cells and cancer metastasis via functioning as a sponge of miR-106a, thereby increasing the levels of adenomatous polyposis coli (APC)." (PMID 38195623, 2024). "In gastric cancer, through its interaction with APC, it negatively regulates canonical WNT signaling, therefore acting as a tumor suppressor similarly to AHNAK." (PMID 38918490, 2024). "LINC01133 was found to be a ceRNA that targets the miR-106a-3p/APC axis to inhibit gastric cancer progression." (PMID 35420507, 2022). "As a ceRNA, LINC01133 regulated APC expression and Wnt/β-catenin pathway by releasing miR-106a-3p to inhibit gastric cancer progression." (PMID 36248984, 2022). "Other conditions involved directly in GC development are gastric adenocarcinoma and proximal polyposis of the stomach, caused by APC promoter 1B mutations, and familial intestinal gastric cancer syndrome (FGC), although no inherited cause has been already identified." (PMID 33525650, 2021). "Fifth, cancers related to the same genetic alteration (eg, both colorectal and gastric cancers are related to the APC gene) inspire us to explore the potential of considering dependent phenotypes of the genetic alteration." (PMID 34032581, 2021). "For instance, LINC01133 functions as a ceRNA in gastric cancer by sponging miR-106a-3p to liberate APC." (PMID 33407499, 2021). "The role of APC methylation in gastric cancer is more controversial than in other gastrointestinal tumors." (PMID 33968756, 2021). "hsa-miR-135b-5p regulates the APC gene in both intestinal and diffuse subtypes of Gastric Cancer (GC)." (PMID 33763302, 2021). "For example, lncRNA LINC01133 played a crucial role in the progression and metastasis of gastric cancer by acting as a ceRNA of miR-106a-3p to regulate adenomatous polyposis coli (APC) expression." (PMID 34794447, 2021). "Among 145 mutations within 31 genes detected in gastroesophageal junction carcinomas and gastric adenocarcinoma, mutations in APC and CTNNB1 are more prevalent among gastric carcinomas, with more than three driver mutations detected in gastric carcinomas." (PMID 34488905, 2021). "For example, Yang et al38 found that LINC01133 inhibited gastric cancer progression and metastasis by acting as a ceRNA for miR‐106a‐3p to regulate APC expression and the Wnt/β‐catenin pathway." (PMID 32583631, 2020).
gastric cancer (continued). "For example, LINC01133 inhibits gastric cancer progression by sponging miR-106a-3p to regulate APC expression and the Wnt–β-catenin pathway." (PMID 33230459, 2020). "Other genes that were commonly mutated in AN gastric cancer patients were PIK3CA, PTEN, KRAS, APC, and CTNN1B, which were comparable to the TCGA study." (PMID 31941061, 2020). "LINC01133 can be combined with miR-106a-3p and then affect the expression of APC, thereby regulating gastric cancer progression." (PMID 30670025, 2019). "Accordingly, methylation of APC occurs in 37.7% of healthy tissues but in 52.9% of gastric cancer samples." (PMID 31248166, 2019). "Studies focusing on gastric cancer patients showed that methylation of ctDNA in SOX17 and APC were independently associated with poor survival." (PMID 30087854, 2018). "Our results also showed that hsa-miR-29c-5p is an important regulator of CDC42 and DNMT3A genes in the intestinal subtype gastric cancer and hsa-miR-135b-5p regulates the APC gene in both intestinal and diffuse subtypes of GC." (PMID 30376837, 2018). "Up-regulation of CDC42 and DNMT3A genes and down-regulation of APC gene in gastric cancer have several implications in the malignancy of the cell." (PMID 30376837, 2018). "The present study suggests the implication of novel APC gene alterations in gastric cancer related with cell cycle abnormalities and APC protein expression in diffuse type gastric cancer." (PMID 28576136, 2017). "Mutations in the Wnt pathway components APC and CTNNB1 were more common among gastric carcinomas (16% vs. 3%, p = 0.006), and gastric carcinomas were more likely to have ≥3 driver mutations detected (11% vs. 2%, p = 0.044)." (PMID 25656989, 2015). "Two components of the Wnt pathway, APC and CTNNB1, were in aggregate mutated more frequently in gastric carcinomas than in GEJ tumors (16% vs. 3%, p = 0.006)." (PMID 25656989, 2015). "Among the 33 gastric cancers with DNA available for analysis, the corresponding number of cases with promoter hypermethylation in primary cancer tissues for APC, E-cadherin, hMLH1 and TIMP3 was 20 (61%), five (15%), 14 (42%) and five (15%)." (PMID 15942635, 2005). "Preferential methylation in the serum DNA of gastric cancer patients was noted in APC (17%), E-cadherin (13%), hMLH1 (41%) and TIMP3 (17%) genes." (PMID 15942635, 2005). "We and others have previously demonstrated the frequent hypermethylation of CpG islands within the promoter regions of genes like hMLH1, E-cadherin, p15, p16, and APC in gastric cancer." (PMID 15942635, 2005). "The Wnt signaling pathway is well known to be involved in maintaining the normal function of the intestinal epithelium, and genetic alterations in key components APC and β-catenin have been linked to the development of CRC, gastric cancer, and other malignancies within the GI tract." (PMID 39936971, 2025). "In particular, the APC variant S1465W was not coincidental because only 10 gastric cancer patients with the single nucleotide variation were deposited in cBioPortal." (PMID 40916582, 2025). "Similarly, LINC01133 attenuated the progression of gastric cancer via sponging miR-106a-3p to alter APC expression and finally inhibit the Wnt/β-catenin signaling pathway." (PMID 38111678, 2023). "APC is hypermethylated in gastric cancer (53%) relative to normal (38%) tissue." (PMID 37943618, 2023).